NRAS (NRAS proto-oncogene, GTPase)
Diseases named in the same sentence as NRAS in open-access papers (continued):
Sharing a sentence is not in itself a finding about the gene and the disease.
melanoma (continued). "In contrast, melanomas from chronically sun-damaged skin or from sites not routinely exposed such as acral or mucosal sites do not typically carry BRAF mutations and would be more associated with NRAS and KIT mutations respectively." (PMID 35712493, 2022). "NRAS represents the most mutated RAS isoform, the vast majority of these mutations being found in codon 61, without correlation with UV-damage signature in melanoma." (PMID 35334544, 2022). "Moreover, it is important to note that, in addition to the classical signatures, atypical UV photoproducts can also be responsible for observed noncanonical oncogenic lesions, even at lower frequencies, in the most common melanoma driver genes, including BRAF and NRAS." (PMID 35804995, 2022). "However, many driver mutations in melanoma (e.g., in the BRAF and NRAS oncogenes) do not fit this UV mutation signature." (PMID 36704334, 2022). "Thus far, no combination therapy for NRAS-mutant melanoma has progressed to phase III clinical trials." (PMID 35954441, 2022). "Interestingly, rearrangements and amplification of the MAP3K8 gene leading to increased levels of the truncated, active form of this protein are detected in approximately 15% of melanomas without driver mutations, such as BRAF, NRAS, or NF1." (PMID 35565444, 2022). "In mucosal melanomas, the BRAF and NRAS mutations are infrequent, which may reflect the lack of sunlight exposure." (PMID 34063141, 2021). "As another example, the preclinical observation that CDK4/6 inhibition can attenuate NRAS oncogenic signaling when combined with MEK inhibition has led to an undergoing clinical investigation of the synergistic inhibition of CDK4/6 (PD-0332991) and MEK1/2 (selumetinib) in NRAS-mutant melanomas." (PMID 34123788, 2021). "Furthermore, in a series of 43 melanoma short-term cultures, we showed that the RICTOR locus was amplified in 19 out of 43 melanoma cell lines (44%) and that amplification was independent of the BRAF and NRAS mutation status." (PMID 34680615, 2021). "However, unlike BRAF mutant melanoma, no targeted therapy has yet been approved for NRAS mutant melanoma so far." (PMID 33732653, 2021). "In addition, the inhibition of ERK phosphorylation significantly enhanced apoptosis in BRAF- and NRAS-mutant melanoma spheroids, but not the wild-type BRAF/NRAS spheroid model." (PMID 33804655, 2021). "Unfortunately, targeted therapies for NRAS mutant melanoma patients are sorely lacking." (PMID 33921974, 2021). "Moreover, NRAS-mutant melanoma, which constitutes ~25% of all melanoma cases, do not significantly benefit from those therapies, as they commonly lack oncogenic BRAF mutations and show a high degree of intrinsic resistance to MEKi." (PMID 34299213, 2021). "There are no clinically approved inhibitors for NRAS mutant melanomas." (PMID 33804655, 2021). "There is currently no targeted therapeutic approach for NRAS-mutant melanomas." (PMID 34944843, 2021). "Moreover, Gene 33 expression does not affect proliferation of melanoma cells containing mutant NRAS." (PMID 34206547, 2021). "However, activation of BRAF or NRAS is insufficient to promote melanoma initiation without senescence bypass mediated by additional founder mutations or expression changes of several genes including p16INK4A, CTNNB1, PTEN, or MDM43–7." (PMID 34140478, 2021). "Non-CSD-associated melanomas encompass acral and mucosal melanomas that usually do not show BRAF, NRAS, or NF1 mutations (triple wild-type), but in a subset may have KIT or SF3B1 mutations." (PMID 34571969, 2021). "In multivariate analysis, NRAS mutation, along with ECOG performance score and LDH level, was negatively associated with both PFS (HR 1.912, P=0.044) and OS (HR 2.210, P=0.025) in noncutaneous melanoma." (PMID 34290710, 2021). "Inhibition of MCL-1 through miR-32 may be an effective anti-melanoma strategy, regardless of the status of NRAS, BRAF or PTEN, as MCL-1 inhibition exhibits synergistic effects with Vemurafenib." (PMID 32054078, 2020).
melanoma (continued). "However, this study also highlights the variability in metabolic rewiring between melanomas with different oncogenic drivers and suggests that mutant BRAF and mutant NRAS may utilize different metabolic pathways for survival benefits." (PMID 32046099, 2020). "These non-canonical mutation classes include NRAS Q61R and BRAF V600K and V600E, which are among the most common driver mutations in melanoma, indicating that mutations caused by atypical photoproducts may promote melanomagenesis." (PMID 33207206, 2020). "However, these current therapies used to treat patients with NRAS‐mutant melanoma are not very efficient, owing to the aggressive nature of tumor cells and complex changes in molecular signaling." (PMID 31549767, 2020). "Our group was the first to show that the Cav3.1 isoform is upregulated in both melanoma cell lines and biopsies from BRAFV600E-mutant melanomas, which was accompanied by increased levels of LC3II protein-important for the autophagic process-compared with NRAS-mutant melanomas." (PMID 32046241, 2020). "For melanoma models presence of BRAFV600E and absence of NRAS mutations may serve as additional predictors for higher tumor-resident pDC probability." (PMID 33013879, 2020). "Around 50% of melanoma patients carry mutations in the BRAF gene and around 30% of patients in the NRAS gene resulting in an over-activation of the mitogen-activated protein kinase (MAPK) pathway, making this signalling cascade one of the most important targets for melanoma therapy." (PMID 32063604, 2020). "hnRNP H2 modulation may also address the lack of therapies for NRAS mutants and other subtypes of melanoma." (PMID 31573152, 2019). "Similarly, a representative BRAF/NRAS wild-type melanoma was also not responsive to BRAF or MEK inhibitors." (PMID 31727958, 2019). "This was independent of the BRAF/NRAS mutation status, and suggests that PAX3 induced MITF expression is an inherent melanocyte lineage trait that is conserved in melanoma independently of the genetic background." (PMID 30277012, 2019). "Furthermore, in a significant proportion of BRAF mutant cases metastases switched from low to high or high to low MAF and such an extreme shift also occurred individually in heterogeneous multiple metastatic BRAF mutant cases, unlike in NRAS mutant melanomas." (PMID 31391014, 2019). "In addition, studies employing a mouse model of melanoma revealed that NRAS Q61R binds PI3K with lower affinity than WT NRAS or NRAS G12D while NRAS G12D and Q61R activate AKT at variable levels, indicating that the activation of the PI3K pathway in melanoma is codon-independent." (PMID 31681616, 2019). "Thanks to the recent advances in deep sequencing, melanomas are now classified at the molecular level depending on the mutational status of their major oncogenic drivers (BRAF, NRAS, and NF1), and are considered as “triple-negative” when no mutations are present in these genes." (PMID 29534457, 2018). "In any case, the function of TCF19 in NRAS‐mutant melanoma, especially in BRAF/MAPK inhibitor and immune therapy resistance, is worthy to study further to better understand the mechanisms of how TCF19 is upregulated in NRAS‐mutant melanoma and how it governs the resistance to immune therapy." (PMID 29661909, 2018). "Similarly, loss of function mutations in the negative PI3K regulators, NF1 and PTEN or activating NRAS mutations, did not significantly reduce the sensitivity of BRAFV600E-mutant melanoma cells to trametinib." (PMID 30237495, 2018). "SR4 and niclosamide inhibited melanoma proliferation irrespective of BRAF/NRAS status." (PMID 30651927, 2018). "Together, these data support the premise that TERT depletion may lead to both telomeric and non-telomeric DNA damage in NRAS-mutant melanoma cells." (PMID 29695835, 2018).
melanoma (continued). "We speculate that the differentiation status of wildtype NRAS/BRAF melanomas impacts on the prognostic utility of ICAM-1, as more than three quarters of the wildtype NRAS/BRAF tumors had high PMEL levels and thus were derived from well differentiated melanocytes." (PMID 30116025, 2018). "Notably, Ets-1 is induced by BRAF or MEK kinase inhibition, resulting in increased NRAS expression, which could be blocked by inactivation of Usp9x and therapeutic combination of Usp9x and MEK inhibitor fully suppressed melanoma growth." (PMID 28198367, 2017). "In summary, CDK4 inhibitor palbociclib may be a strong inhibitor of melanoma cell proliferation in the absence of BRAF and NRAS mutations in melanomas with homogeneous CDK4 expression." (PMID 27903987, 2017). "But, whilst mutant NF1 is known to cooperate with RASopathy genes (RASA2, PTPN11, SOS1, RAF1 and SPRED1) in melanoma and although NF1 is found to be frequently mutated (25–30%) in melanomas harbouring wild-type BRAF and NRAS, it is curious that melanoma is not a tumour type associated with NF1." (PMID 28637487, 2017). "On the one hand, melanomas with chronic sun-induced damage (CSD) harbor mutations in KIT proto-oncogene receptor tyrosine kinase (KIT, Gene ID: 3815), NF1, NRAS, and BRAF but typically not BRAF(V600E), the specific BRAF mutation that commonly arises in atypical melanocytic neoplasms." (PMID 28265786, 2017). "We surveyed kinome expression patterns across sub-populations of the BRAF/NRAS wild type sample and found that CDK4 and CDK2 were consistently highly expressed in the majority of cells, suggesting that these kinases might be involved in melanoma progression." (PMID 27903987, 2017). "It is also possible that NRAS may activate different signaling pathways from KRAS and HRAS, an idea supported by the observation that NRAS has greater transforming activity than KRAS in experimental models of melanoma." (PMID 29349077, 2017). "Importantly, combination of the EPE peptide and trametinib showed synergy in reducing the viability of some NRAS mutant melanomas, an effect driven by the partial preservation of negative feedback loops." (PMID 29180761, 2017). "In vitro studies demonstrate that ERβ ligands inhibit the proliferation of melanoma cells harboring the NRAS (but not the BRAF) mutation, suggesting that ERβ activation might impair melanoma development through the inhibition of the PI3K/Akt pathway." (PMID 27833586, 2016). "Moreover, the pattern of expression of the different ERβ isoforms was similar in BLM (NRAS-mutant, BRAF-wild type) and WM115 (BRAF V600D-mutant) melanoma cells: ERβ1 and ERβ5 were found to be expressed at similar levels while ERβ2 showed a higher level of expression." (PMID 27833586, 2016). "We here identify miR-32/MCL-1 pathway members as key early genetic events driving melanoma progression, and suggest that their inhibition may be an effective anti-melanoma strategy irrespective of NRAS, BRAF, and PTEN status." (PMID 27846237, 2016). "To address the limitations of melanoma therapies, we included multiple tumor samples of patients relapsed from current treatments, with a diverse genetic background (with or without the common BRAF, NRAS or NF1 mutations) in these studies." (PMID 27829238, 2016). "Targeting a hyperactivated MAPK pathway driven by mutated NRAS or BRAF with specific BRAF- and MEK inhibitors, increases the median overall survival from metastasized melanoma patients from 9 months with no therapy to approximately 14 months with successful inhibitor treatment." (PMID 27791198, 2016). "To assess whether melanomas are uniquely sensitive to the synergistic effects of cardiac glycosides and MAPK pathway inhibitors we transplanted human NRAS mutant acute myeloid leukaemia cell lines (HL60 and U937) into NSG mice and monitored disease progression with bioluminescence imaging." (PMID 27545456, 2016).
melanoma (continued). "Compared to tumors without the mutation, the P131L mutant positive tumors were associated with increased thickness (p = 0.02), head and neck (p = 0.009) and upper limb (p = 0.03) location, lentigo maligna melanoma subtype (p = 0.02) and BRAF V600K (p = 0.04) but not V600E or NRAS codon 61 mutations." (PMID 25544760, 2015). "In addition, we tested the status of NRAS and PTEN in human melanoma cell lines." (PMID 26307673, 2015). "Although NRAS mutations have been reported in 14% of human melanoma cell lines and 15–25% of melanoma clinical specimens, nevertheless, HRAS and KRAS mutations are not common in melanoma." (PMID 25695059, 2015). "In conclusion, the presence of NRAS mutation and PTEN loss is not mutually exclusive in melanoma." (PMID 26307673, 2015). "Recently, encouraging results were also reported with agent that targets NRAS mutant melanomas in an open label phase III trial randomizing NRAS-mutant melanoma patients with or without prior immunotherapy 2:1 to binimetinib 45 mg BID (n = 269) or DTIC 1000 mg/m2 every 3 weeks (n = 133)." (PMID 27508107, 2015). "RAC1 is a RAS-related GTPase that regulates cell proliferation and migration; RAC1P29S is a recurrent UV-signature mutation in cutaneous non-acral melanomas and was the third most frequent activating mutation (9.2%) after those of BRAF and NRAS in a large cohort (n=147) of exome-sequenced melanomas." (PMID 25344914, 2014). "Importantly, TREVA has been successful in the molecular subtyping of melanomas, which may direct novel therapeutic options for BRAF/NRAS wild-type patients." (PMID 24752294, 2014). "However, an overexpression of KIT and CDK4 has been identified in a subgroup of cutaneous malignant melanomas and would be a mechanism of potential oncogenic transformation of nonmutated BRAF or NRAS melanomas." (PMID 24416617, 2013). "Interestingly, the most common mutations found in melanomas, in BRAF and NRAS, do not occur as a result of UV-irradiation." (PMID 23303275, 2013). "Besides frequent mutations in growth- and survival-promoting genes like BRAF and NRAS, melanomas additionally harbor complex non-random genomic alterations." (PMID 22535842, 2012). "It has recently been shown that the phospho-ERK staining was not correlated with the mutational status of NRAS and/or BRAF in melanoma tissues, and that cultured BRAF-mutant melanoma cells downregulated RAS/RAF/MEK/ERK activation when cultured at high densities or under non-adherent conditions." (PMID 21224857, 2011). "Even in NRAS or BRAF mutant melanomas, no reduced function or expression of the DNA repair system could be found." (PMID 22007305, 2011). "However, so far, drug induced promotion of cell proliferation was observed in two NRAS mutant primary melanoma cell strains that did not acquire full independence from environmental growth stimuli." (PMID 20149136, 2010). "The pro-apoptotic effects of PLX4720 were found to be BRAF specific, with high levels (>30%) of apoptosis only induced in the BRAF-V600E-mutated melanoma cell line panel (WM35, WM164 and 1205Lu), and not the NRAS-mutated melanoma cell lines (WM1346, WM1361A and WM1366)." (PMID 20531415, 2010). "Furthermore, melanoma cells, regardless of their BRAF or NRAS mutation status, are sensitive to the growth inhibitory effects of 17-AAG, consistent with the action of Hsp90 inhibitors on multiple oncoproteins, including CRAF." (PMID 21037799, 2010).
melanoma (continued). "However immortalization alone is not sufficient to produce melanoma, and it is only when constitutively active β-catenin is combined with deregulated proliferation through NRAS that full-fledged transformation will occur." (PMID 24281103, 2010). "However, we could rule out both pathways as drivers of constitutive IκBζ expression in melanoma, as neither the presence of activating BRAF or NRAS mutations nor increased NF-κB activity correlated with constitutive IκBζ protein expression." (PMID 40562773, 2025). "The preliminary indication of antitumor activity in BRAF-mutated melanoma is promising although further clinical development of single agent use in this setting in tumors that do not harbor RAF fusions (e.g., those with KRAS or NRAS mutations) is likely to be limited." (PMID 37219686, 2023). "However, mutations in NRAS (~30%), but not KRAS (3%) or HRAS (2%), are common in melanomas." (PMID 36901857, 2023). "Apart from the activating NRAS mutations (linked with high NRAS expression) and the inactivating NF1 mutations (linked with decreased NF1 expression), all the other mutations were randomly distributed across all melanoma tumors, irrespective of their gene expression." (PMID 36389735, 2022). "However, there is not specific line of treatment for NRAS mutant melanomas." (PMID 36402789, 2022). "Here we saw that NRAS61R could not initiate melanoma in the presence of wild-type NRAS." (PMID 35672316, 2022). "Therefore, the selective inhibition of BRAF in NRAS mutant melanomas is not an adequate approach, as it can induce the paradoxical activation of RAF proteins and the concomitant ablation of BRAF and CRAF, leading to the emergence of resistant cells showing the ARAF-dependent reactivation of ERK." (PMID 34831002, 2021). "Thus, anti-PD-1 monotherapy may not be enough for patients with NRAS mutant advanced melanoma, especially in noncutaneous subtypes." (PMID 34290710, 2021). "Notably, the efficacy of this combinatorial treatment in melanoma cells is not influenced by BRAF, NRAS or NF1 mutational status, opening the possibility of using these compounds to treat melanoma expressing high levels of SOX2 and GLI1 irrespectively to their mutational status." (PMID 33958721, 2021). "We investigated the IRAK-M DNA methylation profiles of patient samples and melanoma cell lines and found that reduced methylation within the promoter region of IRAK-M correlated with increased transcript levels, neither did they correlate with BRAF or NRAS mutation status, nor CDKN2A genotype." (PMID 32533049, 2020). "Even though both BRAF-mutant A375 and NRAS-mutant WM1366 cells responded similarly to CDK11 down-regulation with respect to loss of cell survival capability and accumulation of G1-phase cells, these 2 types of melanoma did not respond identically at the molecular level." (PMID 30987032, 2019). "In contrast to BRAF-mutated melanoma, no approved targeted therapies exist for NRAS-mutated melanoma, but positive phase III data on PFS have been reported for a study comparing the efficacy of binimetinib (MEK162) versus dacarbazine in unresectable or metastatic NRAS-mutated melanoma (NEMO study)." (PMID 30956763, 2019). "Further exploration of this topic will include multivariate survival analysis to determine if Cks1 is an independent prognostic variable and to evaluate whether Cks1 expression segregates with the presence or absence of specific gene mutations involved in melanoma such as BRAF and NRAS." (PMID 29423113, 2018). "Therefore, the assumption that BRAF but not CRAF could be dispensable for NRAS-induced melanoma appears paradoxical." (PMID 28497782, 2017). "Moreover, our data suggest that their inhibition may be an effective anti-melanoma strategy, irrespective of the status of NRAS, BRAF or PTEN." (PMID 27846237, 2016).